INSR (insulin receptor)
Diseases named in the same sentence as INSR in open-access papers (continued):
Sharing a sentence is not in itself a finding about the gene and the disease.
Insulin resistance (continued). "Notably, deletion of the insulin receptor in myeloid cells reduces macrophage infiltration during HFD, decreases circulating levels of TNF-α and protects against HFD-induced insulin resistance, highlighting insulin’s potential negative role in innate immune responses during MetS." (PMID 39605858, 2024). "Furthermore, liver macrophages contribute to insulin resistance independently of their inflammatory status, through the secretion of IGFBP7, a non-inflammatory factor with a high capacity to bind the insulin receptor and induce lipogenesis and gluconeogenesis through the activation of ERK signaling." (PMID 32526449, 2020). "Moreover, the finding of a negative correlation between transcript levels of INSR and SBP at 5 years of age may be considered in the light of the known link between insulin resistance and hypertension." (PMID 31064394, 2019). "Moreover, high glucose induced insulin resistance by decreasing the phosphorylation of GSK3β, triggering the ubiquitination and degradation of insulin receptor substrate (IRS1), which did not require insulin receptor signaling or PI3K/AKT activity." (PMID 25993471, 2015).
diabetes (388 papers, 2003 to 2026). "Type-2 Diabetes Mellitus (DM) is a complex metabolic disorder characterized by progressive loss of pancreatic β- cell function and insulin receptor sensitivity." (PMID 39810524, 2025). "Historically, Chromosome 1 is known to contain multiple diabetes-associated loci (e.g., regions near INSR)." (PMID 40572705, 2025). "Overall, Type I dInr adults have three features associated with human diabetes: hyperinsulinemia, mechanisms to increase insulin peptide bioavailability, and impaired insulin receptor sensitivity." (PMID 40093182, 2025). "Overall, Type I dInr adults in particular have three features associated with human pre-diabetes: hyperinsulinemia, mechanisms to increase insulin peptide bioavailability, and impaired insulin receptor sensitivity." (PMID 40523036, 2025). "Other cases described a patient with type 2 diabetes mellitus with heterozygous missense mutation in the INSR gene, c.3472C>T (p.Arg1158Trp)." (PMID 40565151, 2025). "This early upregulation of protooncogenic pathways is driven in part by the activity of the insulin receptor, which is highly upregulated in rat diabetes-associated CCTs compared to the surrounding tubular apparatus." (PMID 38791455, 2024). "ADT can also lead to an increased risk of developing diabetes due to reducing the insulin receptor sensitivity, especially when administered for a longer time." (PMID 38312318, 2024). "Considering the phenotypical spectrum of INSR gene variants and the consistently increased insulin levels, our patient will be closely monitored for the potential development of type 2 diabetes mellitus." (PMID 39659391, 2024). "Heterozygous pathogenic variants in the insulin gene can cause monogenic diabetes through effects on the processing of proinsulin to insulin, beta cell function, and/or altered insulin-receptor affinity." (PMID 39027635, 2024). "We evaluated key markers of insulin signaling in skeletal muscles in our population, as skeletal muscle contributes to over 85% of glucose disposal in humans of normal weight, and deficits in proximal insulin receptor signaling are associated with diabetes." (PMID 39684905, 2024). "Type-2 diabetes mellitus (DM) is a complex metabolic disorder, that is characterized by progressive loss of pancreatic β-cell secretory function and insulin receptor sensitivity." (PMID 39036260, 2024). "IGF2, a growth factor capable of binding the insulin receptor and implicated in diabetes, was among the highest transcripts expressed in responding patient tumors (eFigure 6D in Supplement 2)." (PMID 38095878, 2024). "In our study, our focus was to investigate the molecular interactions between myricetin and key regulators implicated in diabetes, including glycogen synthase kinase 3 beta (GSK3β), insulin receptor (IR), and glucose kinase (GCK)." (PMID 38465169, 2024). "Recently, new therapies aimed at handling hyperinsulinemia and diabetes seen in patients with congenital SIR due to INSR mutations and in type A SIR have been proposed." (PMID 36178555, 2023). "For example, the mTOR signaling pathway is related to cancer, and AD; IL-8 signaling is associated with inflammation; insulin receptor signaling is linked to diabetes." (PMID 37550674, 2023). "Most participants with syndromic diabetes in our cohort had relatively distinct phenotypic features suggestive of a monogenic condition, for example the participant with the INSR pathogenic variant who had features typical of Rabson–Mendenhall syndrome." (PMID 37897565, 2023). "INSR gene mutations also underlie the type A insulin resistance syndrome and leads to diabetes mellitus." (PMID 34249083, 2021). "ER stress has been closely associated with the development of insulin resistance and diabetes by impeding insulin receptor signaling and dysregulating pancreatic beta cell survival that are critical factors in the pathogenesis of diabetes." (PMID 34444889, 2021).
diabetes (continued). "So far, a variety of genetic alterations leading to defects in insulin receptor (INSR) and/or other components of the insulin signaling pathway have been recognized as significant causes of uncommon forms of IR and diabetes." (PMID 34681797, 2021). "Osteoblasts isolated from Phospho1−/− mice were enriched for genes associated with energy metabolism and diabetes; Phospho1 both directly and indirectly interacted with genes associated with glucose transport and insulin receptor signalling." (PMID 33092598, 2020). "In this study, we report three different families presenting with variable clinical manifestations, ranging from neonatal HH to adult onset type 2 diabetes mellitus, associated with heterozygous INSR mutation." (PMID 31989990, 2020). "Keeping with the theme of insulin receptor signaling, Nicolas Rohner and colleagues used a rather unconventional model to study diabetes-associated pathologies, namely the cave-dwelling fish species A. mexicanus (cavefish)." (PMID 31686269, 2019). "We also detected a combination effect between genetic variants of GCK or INSR and chronic heavy alcohol consumption on the incidence of diabetes (p = 0.0029 and 0.0044, respectively)." (PMID 31882596, 2019). "In this study, we found that chronic heavy alcohol consumption influenced the associations between INSR variants and the incidence of diabetes." (PMID 31882596, 2019). "We identified that these GCK and INSR polymorphisms are affected by chronic heavy alcohol consumption and have an effect on the incidence of diabetes." (PMID 31882596, 2019). "Impaired insulin receptor (IR) signaling has been associated with a number of pathological conditions including diabetes, hypertension, and renal disease." (PMID 27923977, 2016). "Defective hepatic insulin receptor (IR) signalling is a pathogenic manifestation of metabolic disorders including obesity and diabetes." (PMID 26387534, 2015). "In the milieu of diabetes mellitus, impaired insulin receptor signaling and loss of neurotrophic signals deteriorate cell survival and cell–cell interactions at synapses." (PMID 24905410, 2014). "Previously, we reported that defects in HMGA1 caused decreased insulin receptor expression and increased susceptibility to type 2 diabetes mellitus in humans and mice." (PMID 25628604, 2014). "Recently, fast, fatigable, glycolytic muscle has been linked to insulin receptor resistance and diabetes." (PMID 24744911, 2014). "We have previously reported that streptozotocin-induced diabetes in the rat retinas led to decreased insulin receptor and Akt phosphorylation, which was associated with increased apoptotic levels." (PMID 23592917, 2013). "The loss-of-function Gly972Arg SNP decreases IRS-1 activity and inhibits INSR autophosphorylation and activity, increasing the risk of IR and diabetes." (PMID 23394097, 2013). "The ENPP1 Lys121Gln gain-of-function polymorphism enhances the interaction between the ENPP1 glycoprotein and insulin receptor (INSR), contrasting INSR kinase activity, and is associated with an increased diabetes risk." (PMID 23394097, 2013). "As we previously reported, HMGA1 is a main activator of the INSR gene, and individuals with defects in HMGA1 have decreased INSR expression and increased susceptibility to type 2 diabetes mellitus." (PMID 24367622, 2013). "Cognitive impairments associated with diabetes caused by inadequate insulin/insulin receptor functions have also been documented." (PMID 20868513, 2010). "Diabetic peripheral neuropathy (DPN), a complication of diabetes mellitus (DM), is a neurodegenerative disorder that results from hyperglycemic damage and deficient insulin receptor (IR) signaling in peripheral nerves, triggered by failure of insulin production and insulin resistance." (PMID 39381501, 2024). "Besides, cytokine including adiponectin and INSR presented interesting association with diabetes due to the crucial correlation with IGF1 in our study." (PMID 38375323, 2024).
diabetes (continued). "In terms of signaling pathways, and in cases of diabetes, reduced insulin levels and reduced insulin receptor expression are associated with AD and the defective activation of the insulin/IGF-1/PI3K/Akt pathway of intracellular signals, which is a major effector for insulin’s action in the brain." (PMID 39769243, 2024). "This would have given an indication as to whether our findings also apply to healthy individuals and, consequently, whether analyses of SNPs in INSR may be useful in identifying individuals at risk of developing severe diabetes." (PMID 35742925, 2022). "Insulin receptor (IR) signaling defects cause a variety of metabolic diseases including diabetes." (PMID 36151101, 2022). "The retinal insulin receptor (IR) exhibits basal kinase activity equivalent to that of the liver of fed animals, but unlike the liver, does not fluctuate with feeding and fasting; it also declines rapidly after the onset of insulin-deficient diabetes." (PMID 33915127, 2021). "However, antagonizing aAb are also described, e.g., in type B insulin resistance, where aAb to the insulin receptor impairs insulin effects, causing a form of diabetes that is refractory to therapeutic insulin application." (PMID 31940750, 2020). "Altered INSR expression causes IR and diabetes in humans and mice." (PMID 32425888, 2020). "First, to our knowledge, this is the first investigation of the effects of the interactions between GCK/INSR genetic variants and chronic alcohol consumption on the incidence of diabetes using 12-year follow-up data, providing a detailed analysis based on glycemic index data obtained from OGTTs." (PMID 31882596, 2019). "Therefore, we evaluated the effects of the interactions between GCK and INSR single-nucleotide polymorphisms (SNPs) and chronic heavy alcohol consumption on β-cell function, insulin sensitivity, and development of diabetes in a 12-year follow-up cohort study." (PMID 31882596, 2019). "We aimed to determine whether the longitudinal associations between genetic variants of glucokinase (GCK) and insulin receptor (INSR) and the risk of developing diabetes were influenced by chronic heavy alcohol consumption." (PMID 31882596, 2019). "Hyperglycaemia in patients with insulin receptor mutations is extremely difficult to treat, and patients are at risk for early morbidity and mortality from the microvascular complications of diabetes." (PMID 29695048, 2018). "The association between ABO and the insulin receptor suggests that INSR-mediated insulin signalling may be involved in the ABO-diabetes association." (PMID 28240269, 2017). "We have shown that retinal insulin receptor signaling is disrupted in insulin-deficient diabetes but it was unclear whether it results from hyperglycemia and/or hypoinsulinemia." (PMID 22046295, 2011). "these genomic actions of 1,25D3 could represent beneficial effects associated with the amelioration of diabetes via mechanisms that possibly involve direct transcriptional activation of the rat insulin receptor gene." (PMID 18638371, 2008). "There is no specific explanation for the hypercalciuria, however it resembles the insulin-reversible hypercalciuria associated with diabetes, pointing to an involvement of INSR activation in the control of urine calcium excretion, however it could be also secondary to glucosuria." (PMID 40241988, 2025). "Diabetes mellitus (DM) is a chronic and progressive condition defined by hyperglycemia caused by abnormalities in insulin production, insulin receptor sensitivity, or both." (PMID 36890575, 2023). "Single nucleotide polymorphisms (SNPs) in insulin and insulin receptor genes may influence the interaction between the two molecules, as may anti-insulin antibodies (IAs), commonly found in patients with type 1 diabetes mellitus (T1D) or type 2 diabetes mellitus (T2D) treated with exogenous insulin." (PMID 35742925, 2022).
diabetes (continued). "However, insulin, insulin mimics, or orthosteric InsR activators may increase the risk of hypoglycemia in patients with diabetes, potentially leading to worse glycemic control in patients." (PMID 35502441, 2022). "We will discuss the link between the BBB, oxidative stress, insulin receptor signaling, and two diseases closely associated with insulin resistance: diabetes mellitus (DM) and Alzheimer’s disease (AD)." (PMID 34829566, 2021). "Animal models of diabetes and obesity show an approximate 50% decrease in INSR kinase activity and binding affinity in AT, and diabetic individuals show an overt reduction of the INSR tyrosine kinase activity associated with decreased INSR protein content in adipocytes." (PMID 30754657, 2019). "Altogether, these data, along with the recently reported ability of the enzyme to enhance INSR signaling in myeloma, prompted us to hypothesize that heparanase may play an important role in diabetes-associated breast cancer, facilitating tumor aggressiveness under hyperinsulinemic state." (PMID 28038446, 2017). "However, in three mouse diabetes models of insulin action deficiency, including streptozotocin-induced diabetes and liver insulin-receptor knockout, the expression of PGC-1α was strongly induced, which could lead to increased Sepp1 expression." (PMID 23760059, 2013). "Their antidiabetic effect on streptozotocin-induced diabetes was assessed in rat model with emphasis on blood glucose regulation, insulin receptor expression, GLUT4 levels, PI3K/AKT signaling, PKC/MAPK activity, and inflammatory biomarkers." (PMID 41964775, 2026). "The research on the pathogenesis of diabetes has shifted from insulin receptor damage to the insulin receptor signaling path." (PMID 40362436, 2025). "Reported studies have illustrated that the modulation of NEU1 can have profound implications for insulin receptor activation, thereby influencing metabolic pathways critical in conditions such as obesity and diabetes." (PMID 40573316, 2025). "Researchers have been exploring new ways to treat diabetes by targeting the insulin receptor (IR), a protein that insulin binds to." (PMID 40603733, 2025). "Recent investigations show the role of NEU1 in regulating insulin receptor activity, where its inhibition can enhance insulin signaling, providing a promising intervention for metabolic disorders such as diabetes." (PMID 40573316, 2025). "In diabetes, furin downregulation potentially leads to insulinresistance by reducing maturation of the insulin receptor." (PMID 38481703, 2024). "STUB1 has been shown to regulate diabetes through the degradation of INSR, and we demonstrated another mechanism to control insulin signaling." (PMID 38970167, 2024). "Enrichment of amino acid metabolism was previously reported from GDM mothers, which are involved in insulin receptor signalling and glucose metabolism, indicating the importance of metabolomic interactome in diabetes or GDM development." (PMID 38684759, 2024). "In this study, we conducted two-sample MR analyses using multiple GWAS datasets to assess the relationship between individual IGF family members, adiponectin, INSR and diabetes." (PMID 38375323, 2024). "PTP1B overexpression can cause a decrease in insulin receptor phosphorylation, and mutations in the PTP1B gene can lead to diabetes, making its inhibitor a potential diabetes treatment." (PMID 38790018, 2024). "Type 2 diabetes mellitus (T2DM) is a chronic and progressive condition defined by hyperglycemia caused by abnormalities in insulin production, insulin receptor sensitivity, or both." (PMID 38232103, 2024). "To date, different levels of INSR expression have been reported in several physiologic and pathologic states, including diabetes, depending on tissue type and environmental perturbations." (PMID 39684804, 2024).